C3 (complement C3)
Diseases named in the same sentence as C3 in open-access papers (continued):
Sharing a sentence is not in itself a finding about the gene and the disease.
liver cirrhosis (6 papers, 2019 to 2024). "Furthermore, tumor stage, albumin, liver cirrhosis, and complement C3 with hybrid glycoform were associated with the mortality rate of HCC." (PMID 31136099, 2019). "Chronic hepatitis B infection disrupts both the innate and adaptive immune systems, which contributes to liver cirrhosis due to decreased production of complement proteins like C3 and C4." (PMID 39735192, 2024). "Baumann and colleagues showed that serum complement concentrations of C3 and C4 correlated negatively with the severity of liver cirrhosis." (PMID 33585012, 2020). "Of these, eight proteins, glypican 3 (GPC3), squamous cell carcinoma antigen (SCCA), haptoglobin, C3 precursor, seprase, hemoglobin subunit gamma, hemoglobin subunit alpha, and teneurin-3, showed higher relative peaks in HCC cases with normal AFP levels than the liver cirrhosis controls." (PMID 31979338, 2020).
meningococcal infection (6 papers, 2008 to 2024). Infections with bacteria of the species neisseria meningitidis. "C3NeF can also be found in other conditions such as acquired partial lipodystrophy and an increased susceptibility to meningococcal infections secondary to persistently low C3 concentrations resulting from C3 consumption." (PMID 30405598, 2018). "In meningococcal infection, for instance, C3 activation and TCC are both increased, with a strong correlation between complement activation and levels of endotoxins produced by Neisseria meningitidis." (PMID 27718086, 2017). "However, C3 degradation fragments physiologically promote opsonization and phagocytosis which are also important for defense against meningococcal infections." (PMID 34177949, 2021). "Therefore, it is not surprising that deficiency of C3 is associated with increased susceptibility to meningococcal disease." (PMID 19388162, 2008).
Microscopic hematuria (6 papers, 2019 to 2024). Microscopic hematuria detected by dipstick or microscopic examination of the urine. "Biomarkers such as microscopic hematuria, persistent proteinuria, serum IgA levels, and the serum IgA/C3 ratio have been identified as effective for distinguishing IgAN from other kidney diseases." (PMID 38816457, 2024). "Originally, Maeda reported that the serum IgA/C3 ratio, combined with microscopic hematuria and/or proteinuria and high serum IgA levels, can be used to distinguish IgAN from other primary renal diseases." (PMID 35585099, 2022). "The gender distribution, age of onset, kidney function, lever of serum C3, C4, and microscopic hematuria frequency were comparable in the two groups (p > 0.05)." (PMID 36611910, 2022).
myopia (6 papers, 2019 to 2025). "This study highlights the role of TGF-β2 in promoting myopia through the activation of complement components C3 and C5 and suppression of CD55, leading to enhanced inflammasome activity." (PMID 40862775, 2025). "Results showed that TGF-β2 exacerbated myopia by upregulating complement components C3 and C5, suppressing CD55, and activating inflammasome pathways through nuclear factor (NF)-κB signaling, leading to axial elongation and increased refractive errors." (PMID 40862775, 2025).
non-small cell lung carcinoma (6 papers, 2020 to 2026). A group of at least three distinct histological types of lung cancer, including non-small cell squamous cell carcinoma, adenocarcinoma, and large cell carcinoma. "Here, we revealed that complement component 3 (C3) is remarkably upregulated in paclitaxel (PTX)-resistant non-small cell lung cancer (NSCLC) cells and that knockdown of C3 promoted PTX-induced cell apoptosis, sensitizing resistant cells to PTX therapy." (PMID 37291119, 2023). "In conclusion, our research indicates that LYN, C3, COPG2ITL, HLA.DQAL, and TNFRSFL17 are potential prognostic markers for non-small cell lung cancer." (PMID 33215029, 2020). "LYN, C3, COPG2IT1, LA.DQA1, and NFRSF17 may be new immune markers to judge the prognosis of patients with non-small cell lung cancer." (PMID 33215029, 2020). "In previous reports, C3 was demonstrated as a potential prognostic marker for non-small cell lung cancer and may be a new immune marker to differentiate the prognosis of patients with non-small cell lung cancer." (PMID 34266404, 2021).
pneumococcal infection (6 papers, 2013 to 2023). Infections with bacteria of the species streptococcus pneumoniae. "Deficiency of C3 is associated with increased susceptibility to meningococcal and pneumococcal infections." (PMID 23843682, 2013). "Therapeutic inhibition of C3, however, might leave some vaccinated subjects with increased risk of acquiring pneumococcal infections, when vaccine-induced antibody levels are low." (PMID 34707606, 2021). "Streptococcus pneumonia infection of CNS is kept in check by complement system (mainly C1q and C3)." (PMID 23843682, 2013).
retinal disease (6 papers, 2008 to 2022). "Dysregulation of C3 plays a highly significant role in retinal diseases, and dysregulation of complement is highly associated with risk of AMD." (PMID 24134095, 2013). "Three genes were chosen from a group of human retinal disease genes: C3 (already included), dystrophin, muscular dystrophy (DMD) and PRP3 pre-mRNA processing factor 3 (Prpf3)." (PMID 18989387, 2008). "However, the function of C3 in DNA-alkylating agent-induced retinal disease is unclear." (PMID 35676725, 2022).
systemic vasculitis (6 papers, 2010 to 2024). "Four patients had active vascular lesions: 2 had a necrotizing vasculitis (patients #2 and #11), and 2 had immune deposits of IgG, IgM, C3 and C1q in vascular walls (patient #2 and #9)." (PMID 35172758, 2022). "Henoch–Schönlein purpura (HSP) is a systemic vasculitis that is characterized by the deposition of IgA-containing complex and complement component 3 (C3) on arterioles, capillaries, and venules." (PMID 29751784, 2018). "Serum levels of complement component 3 (C3) are known to be elevated in systemic vasculitis." (PMID 36292253, 2022).
Ureteral obstruction (6 papers, 2018 to 2025). Obstruction of the flow of urine through the ureter. "In contrast, C3 deficiency significantly reduces renal interstitial fibrosis by inhibiting inflammatory responses in the mouse ureteral obstruction model." (PMID 33971198, 2021). "Studies have found that the synthesis of complement C3 in renal tubular epithelial cells of mice with unilateral ureteral obstruction increases, and the expression of complement receptor C3AR1 in mesenchymal cells increases." (PMID 34735495, 2021). "In mouse models of UUO (unilateral ureteral obstruction), we found that local C3 was constitutively expressed throughout the kidney in the interstitium, from which it was released by F4/80+macrophages." (PMID 30405606, 2018).
bacterial meningitis (5 papers, 2015 to 2025). Inflammation of the membranes surrounding the brain and spinal cord due to a bacterial infection. "At the second node, the presence of C-reactive protein, and complement C3 in the CSF are associated with the diagnosis of bacterial meningitis, and their absence points to enteroviral meningitis." (PMID 26040285, 2015). "In CNS inflammation, elevated levels of C3 in CSF in humans and mice with bacterial meningitis have been previously reported." (PMID 26822321, 2016). "Our results also agree with other works reporting high concentrations of complement C3 in the CSF of patients with bacterial meningitis compared to patients with enteroviral meningitis and controls without infection in the CNS." (PMID 26040285, 2015). "In patients and mice with bacterial meningitis, FH concentrations were elevated during disease and Cfh−/− mice with pneumococcal meningitis had increased mortality compared to wild-type mice due to C3 depletion." (PMID 31883521, 2019). "The authors propose an algorithm to predict bacterial meningitis based on elevated apolipoprotein A1, also found to be elevated in bacterial meningitis by Song and colleagues, and complement C3, which participates in clearance of encapsulated microbes and in clearance of neuronal synapses." (PMID 28670576, 2017). "In addition, a report analyzing 19 patients with bacterial meningitis demonstrated that complement values such as CH50, C3, and C4 of all patients were within the normal range." (PMID 40539044, 2025).
bipolar disorder (5 papers, 2018 to 2025). A disorder of the brain that causes unusual shifts in mood, energy, activity levels and the ability to carry out day-to-day tasks. "This study investigates the interrelations among complement component 3 (C3) levels, hippocampal function, and mood symptoms among offspring of bipolar disorder (BD) parents who carry familial risk of mood disorders." (PMID 40891026, 2025). "The aim of this study is to explore the changes and clinical significance of serum C3, C4, hypersensitive C-reactive protein (hsCRP) and uric acid (UA) in patients of bipolar disorder (BD)." (PMID 30186190, 2018).
cataract (5 papers, 2017 to 2024). Partial or complete opacity of the crystalline lens of one or both eyes that decreases visual acuity and eventually results in blindness. "Congenital cataract samples also demonstrated an upregulation of C4 proteins, while posterior polar cataracts presented upregulated C3 proteins and posterior polar C1r proteins." (PMID 37240389, 2023). "In African Americans with POAG, five complement proteins were significantly elevated in the AH samples compared to those with cataracts: C4A (FC = 2.33, p = 0.027), C4B (FC = 1.69, p = 0.015), complement component C7 (FC = 1.38, p = 0.025), F2 (FC = 1.31, p = 0.023), and C3 (FC = 1.21, p = 0.027)." (PMID 37763167, 2023). "It is worth noting that C3b/iC3b but not C5a was detected in the aqueous humour of cataract patients and the intraocular level of C5a did not correlate with C3b/iC3b in RVO patients, suggesting that C3 cleavage does not necessarily lead to C5 cleavage inside the eye." (PMID 39587546, 2024).
cervical cancer (5 papers, 2009 to 2024). A primary or metastatic malignant neoplasm involving the cervix. "C3 cleavage products were extensively deposited along the tumor vasculature in a mouse model of cervical cancer." (PMID 31787848, 2019). "Thus, it is possible that in the case of cervical cancer, complement system proteins, including C3, may act as coadjuvants in the development of lesions into the disease." (PMID 25009667, 2014).
chlamydial infection (5 papers, 2012 to 2021). "These discoveries illuminate the mechanism of a C3-independent C5 activation induced by chlamydial infection, and furthermore provide a potential therapeutic target and drug for preventing tubal fibrosis caused by chlamydial infection." (PMID 35087765, 2021). "The current study aimed to explore the mechanism of C3-independent C5 activation induced by chlamydial infection." (PMID 35087765, 2021). "These discoveries reveal the mechanism of C3-independent C5 activation induced by chlamydial infection, and furthermore provide a potential therapeutic target and drug for preventing tubal fibrosis caused by chlamydial infection." (PMID 35087765, 2021). "We therefore hypothesized that CPAF might be the C3-independent C5 convertase during chlamydial infection." (PMID 35087765, 2021). "Surprisingly, the first compound we investigated, sulforaphane—a key compound in broccoli and other cruciferous vegetables, promoted chlamydial infection by suppressing mitochondrial protein sulfenylation and inducing activation of complement C3 in mammalian host cells." (PMID 33287170, 2020). "Western blot analysis revealed that NM completely blocked the C3-independent C5 activation triggered by different dilutions of C. trachomatis-HeLa229 cell lysates, suggesting that NM had an inhibitory effect on the C5 activation induced by chlamydial infection." (PMID 35087765, 2021). "In the C3−/− mice the lung tissue concentrations of IFN-γ and TNF-α, two key cytokines in the defense against chlamydia, and of IL-6 and IL-10, were either similar to or even higher than for WT controls." (PMID 23189195, 2012). "We know already from former experiments (under slightly different experimental conditions), that, compared to C3+/+ mice, there are much higher numbers of chlamydia on day 9 (but not on day 4) in the lungs of C3−/− mice." (PMID 33767691, 2021). "Intriguingly, the mixed WT recipient was frequently closer to the WT➔WT phenotype than the mixed C3−/− recipient: For instance, only in C3−/−➔WT, but not in WT➔C3−/− mice, the amount of chlamydia in the lung was lower than in C3−/−➔C3−/− animals." (PMID 33746963, 2021). "This combination of results indicated that CPAF participated in a C3-independent C5 activation during chlamydial infection, but not distinguished between the two possibilities: 1) CPAF directly cleaved C5." (PMID 35087765, 2021). "A C3-independent C5 activation pathway was previously demonstrated to contribute to tubal fibrosis induced by chlamydial infection, but the mechanism by which chlamydial infection activates C5 in the absence of C3 remains to be elucidated." (PMID 35087765, 2021). "However, the mechanism of how chlamydial infection activates C5 in the absence of C3 has yet to be elucidated." (PMID 35087765, 2021). "The adequate amounts of C5bCt-9 produced in a short time in vitro relied on the co-existence of traditional C3-dependent C5 convertase cleaving at the R751 site, which appears to contradict the phenomenon that C3−/− mice have no resistance to hydrosalpinx after chlamydial infection." (PMID 35087765, 2021). "However, it is not known how chlamydial infection activates C5 in the absence of C3." (PMID 35087765, 2021).
dermatomyositis (5 papers, 2021 to 2026). Dermatomyositis (DM) is a type of idiopathic inflammatory myopathy characterized by evocative skin lesions and symmetrical proximal muscle weakness. "Such an inhibition limits the available C3 molecules for further incorporation into the C5 convertase assembly, thereby preventing the formation and in situ deposition of MAC, as confirmed in the repeated muscle biopsy specimens of dermatomyositis patients treated with IVIg." (PMID 34766257, 2021).
dry eye (5 papers, 2016 to 2024). "The major finding of this study was that the severity of dry eye syndrome in these patients was strongly correlated with anti-dsDNA and C3 but not with C4, ESR, and ANA." (PMID 27428227, 2016). "The major finding of this study was that the severity of dry eye syndrome in SLE patients without sSS was strongly correlated with anti-dsDNA and C3 but not with C4, ESR, and ANA." (PMID 27428227, 2016).
fungal infection (5 papers, 2020 to 2025). "Previous studies showed that male gender, fungal infection, elevated 24-h urine protein, elevated absolute lymphocyte count, and low C3 level increased the risk for death from PI in patients with SLE." (PMID 34660641, 2021). "In the control sample, only a faint band migrating at the 120 kDa region could be detected compared to the patient's tear, indicating the induction of C3 upon fungal infection." (PMID 32435625, 2020).
HELLP syndrome (5 papers, 2015 to 2025). A life-threatening condition that can potentially complicate pregnancy. "On the other hand, any decreased level of C3 ever documented in our patients showed an inverse association with the occurrence of pre-eclampsia/HELLP syndrome during the subsequent pregnancies." (PMID 32796552, 2020).
hematoma (5 papers, 2022 to 2025). A hematoma is a collection of blood from a vascular structure into an extravascular space. "Furthermore, C3-deficient mice had fewer HO-1 positive cells around the hematoma after ICH." (PMID 36189326, 2022). "Our findings revealed that plasma C3 levels are positively correlated with hematoma volume (r = 0.279, p < 0.05) and the NIHSS score (r = 0.42, p < 0.0001), but are negatively correlated with the GCS score (r = −0.453, p < 0.0001) after ICH." (PMID 38532579, 2024). "We further investigated the relationship between plasma C3 levels and hemorrhagic severity, as indicated by hematoma volume, NIHSS score and GCS score, in this cohort of ICH patients." (PMID 38532579, 2024). "We then used Spearman's correlation coefficient to verify the correlations between plasma C3 levels and hematoma volume, NIHSS score, and GCS score in these patients." (PMID 38532579, 2024). "Understanding how aging and complement C3 impact MGCs may provide important insights into how to regulate hematoma resolution." (PMID 38927458, 2024). "Moreover, the levels of C3 and C1q were higher in patients with larger hematoma volumes." (PMID 36189326, 2022). "The results revealed serum C3 was increased in ICH patients, and the levels of serum C1q and C3 serum were positively correlated with hematoma volume." (PMID 36189326, 2022). "Interestingly, we found that the larger the hematoma volume and NIHSS score were, the higher the plasma C3 level was." (PMID 38532579, 2024). "Moreover, patients with high plasma C3 levels had larger hematoma volumes, higher NIHSS scores, and lower GCS scores than those with high plasma C3 levels according to multiple logistic regression analysis, indicating poor clinical outcomes after ICH." (PMID 38532579, 2024).
hepatitis C (5 papers, 2009 to 2024). "Of the various proteins identified, the one most closely linked to human hepatitis C is C3." (PMID 19664232, 2009). "Previous studies have documented alterations of the complement pathway in human hepatitis C; indeed, plasma C3 has been proposed as a marker for activity in this disease." (PMID 19664232, 2009). "Immunofluorescence shows co-dominance of both IgG and C3 and occasionally IgM (e.g., hepatitis C related MPGN) or a “full house” pattern (including IgG, IgM, IgA, C1q, C3, C4 and kappa and lambda light chains) as seen in SLE." (PMID 32478016, 2020). "Non-PD organoids had down-regulation of C3, which has been reported in patients with hepatitis C infection." (PMID 34358063, 2021).
macular degeneration (5 papers, 2021 to 2022). Loss of vision in the central portion of the retina (macula), secondary to retinal degeneration. "We have previously demonstrated that C3 blockage prevents the formation of sub-RPE deposits in a mouse model of EFEMP1-associated macular degeneration." (PMID 34001980, 2021).